IL10 (interleukin 10)
Diseases named in the same sentence as IL10 in open-access papers (continued):
Sharing a sentence is not in itself a finding about the gene and the disease.
E. coli infection (20 papers, 2010 to 2025). "After 9 h, PGD2 treatment significantly increased TNF-α, IL-1β, IL-6, and IL-8 levels compared to the E. coli infection group, while IL-10 levels decreased." (PMID 40874199, 2025). "As expected, E. coli infection upregulated IL-10 signaling in macrophages, though the level of significance was as modest as FDR q = 0.096." (PMID 36891292, 2023). "As expected, the levels of IL-6, TNF-α, IL-10, and the neutrophil chemoattractant keratinocyte-derived chemokine (KC) were increased in the sera of virgin control mice after E. coli infection." (PMID 33622714, 2021). "Succinate- and itaconate-treated BMDMs display decreased secretion of anti-inflammatory IL-10 in response to E. coli infection, compared to untreated BMDMs, while IL-10 secretion in lactate-treated BMDMs remain indifferent." (PMID 34350128, 2021). "E. coli infection triggered a massive increase in transcript levels for Ccl2, iNos or Il6, a modest increase in Il10 transcripts but totally abrogated IL4 transcript expression in both Sham- and CLP-operated mice." (PMID 32425929, 2020). "Further more, conspicuous differences were also observed in numbers of IL-10-secreting Tregs among the three E. coli infection groups." (PMID 23536867, 2013). "We found that percentages of CD4+CD25+Foxp3+ Tregs in CD4+ PTLN cells were significantly elevated by E. coli infection, along with the enhanced IL-10 secretion." (PMID 23536867, 2013). "1-MT treatment normalized the IL-10 release of LPS-stimulated splenocytes of stressed mice which was paralleled with an improved defense of experimental E. coli infection." (PMID 20689575, 2010). "Our results suggest that increased IL-10 levels in early E. coli infection may act as a compensatory response to innate immune overactivation, whereas its upregulation in later stages reflects PGD′2s anti-inflammatory action." (PMID 40874199, 2025). "Subsequently, PGD2 may bind to the DP1 receptor, exerting an anti-inflammatory effect that mitigates tissue damage by downregulating pro-inflammatory mediators and upregulating IL-10 secretion during E. coli infection." (PMID 40874199, 2025). "However, at 12 and 24 h post-infection, PGD2 significantly downregulated the secretion of TNF-α, IL-1β, and IL-8 compared to the E. coli infection group, while the secretion of IL-6 and IL-10 remained elevated (P < 0.01)." (PMID 40874199, 2025). "The expression of TLRs in BF of chicks treated with HQD were up-regulated, indicating that HQD regulates the anti-infection ability by increasing the mRNA levels of TLR4, -5 and -15, further decreasing the serum LZM and IL-1β, TNF-α, IL-10, IL-6 level of chicks suffered E. coli infection." (PMID 36198724, 2022). "Further, phagocytic cells of the natural immune system secrete IL-10 due to E. coli infection." (PMID 34903932, 2021). "E. coli infection is attributed to IL10 secretion and CD163 up-regulation in PBMΦ-0 and PBMΦ-IL10." (PMID 31953452, 2020). "Based on our findings, BLP could be contributed to attenuating the proinflammatory cytokine (TNF-α and IL-1β) and chemokine (RANTES) production and enhancing anti-inflammatory cytokine (IL-10) production in mouse sera, lungs, and livers after E. coli infection or LPS stimulation." (PMID 36916913, 2023). "In this study, E. coli infection resulted in elevated levels of TNF-α, IL-1β, and IL-6, accompanied by decreased IL-10 levels in the JM group, consistent with findings in animals induced with bacterial and Lipopolysaccharide challenges." (PMID 39199953, 2024). "It is well known that the anti-inflammatory cytokines TGFβ and IL10 improve epithelial permeability and block the negative effects of E. coli infection." (PMID 39409727, 2024). "However, compared with uninfected mice group, significant differences in the mRNA expression of IL-10 in jejunum, colon, and spleen and TNF-α in jejunum and spleen were observed in treated MccJ25 mice group after clinically source MDR E. coli strains infection." (PMID 35250983, 2022).
E. coli infection (continued). "The anti-inflammatory cytokine genes for both IL10 and IL13 were expressed at very low levels and there was no significant increase in their expression 3 h after inoculation, while expression of genes for receptors for both these cytokines increased in response to E. coli infection." (PMID 26572250, 2015). "However, in vitro models of E. coli infection demonstrating that infected BDCA-1+ mDCs, but not Mo-DCs, impair T cell proliferation in an IL-10 dependent manner, provide further evidence that findings in Mo-DCs may not reflect the function of primary mDCs." (PMID 23829893, 2013).
emphysema (20 papers, 2012 to 2025). "In summary, we report that IL10 deficiency results in age‐progressive emphysema and LA development in the murine lung, potentially representing a model of age‐associated COPD emphysema." (PMID 32170906, 2020). "We report that IL10 deficiency accelerates the development of aging‐related emphysema and induces progressive lymphoid aggregate formation in the lung." (PMID 32170906, 2020). "The inverse association between IL-10 transcripts and emphysema extent we found is particularly significant given the independent role of emphysema in mortality." (PMID 24805101, 2014). "These suggest that the exaggerated immunosenescent milieu of IL10 deficiency creates a hospitable environment for reduced alveolar epithelial survival, altered lymphoid dynamics, and macrophage infiltration culminating in lymphoid dysmorphogenesis and emphysema." (PMID 32170906, 2020). "Although our model was elastase-induced emphysema, we found an increase in IL-10 in the airway and in the alveolar septum compared to the control." (PMID 37965351, 2023). "We further examined the levels of mRNA expression from pro-inflammatory cytokines (IL-1β and TNF-α) and an anti-inflammatory cytokine (IL-10) in the whole lungs of an emphysema model." (PMID 34425800, 2021). "We demonstrate that the systemic loss of the IL10 enhances MMP12 expression in the lung and reduces the macrophage prosurvival effects on alveolar epithelial cells, both of which contribute to the emphysema phenotype." (PMID 32170906, 2020). "We show for the first time that the loss of IL10 increases expression of MMP12, an elastase known to contribute to clinical emphysema." (PMID 32170906, 2020). "Ghrelin also increased the M2 subpopulation in emphysema animals and increased IL-10 levels, thus contributing to a reduction in the inflammatory process." (PMID 29100513, 2017). "Tumor necrose factor (TNF) –α, interferon-γ and various classes of interleukins as the IL-1β, IL-6, IL-8, IL-10, IL-17, IL-18, IL-32 and others are involved in the progression of emphysema." (PMID 27775634, 2016). "Consequently, IL-10 and CC-16 are very important factors that regulate the development of emphysema." (PMID 39052574, 2024). "IL-10 polymorphisms have been associated with airflow obstruction (but not emphysema) in some but not all studies, suggesting a possible genetic basis." (PMID 24805101, 2014). "Further analysis identified associations of deficient IL-10 with emphysema versus IFN-γ with airflow obstruction without emphysema." (PMID 24805101, 2014). "We identified significant independent correlations of levels of unstimulated mRNA transcripts in lung CD4+ T cells with specific COPD phenotypes: reduced IL-10 transcripts were associated with emphysema, whereas pervasive absence of T-cell polarization was associated with airflow obstruction." (PMID 24805101, 2014). "The lung-protective effect of HX110B was further tested by determining the expression levels of IL-10, CC16, SP-D, and sRAGE, which have been reported to ameliorate the pathological manifestations of emphysema." (PMID 39052574, 2024). "We found that basal levels of mRNA transcripts for IL-10 and IFN-γ in lung CD4+ T cells were unrelated in individual subjects, and were inversely correlated with emphysema extent vs. spirometry, respectively." (PMID 24805101, 2014). "In an elastase-induced emphysema model, the level of IL-10, but not those of inflammatory cytokines, was higher in LILRB4−/− mice compared with wild-type mice." (PMID 34425800, 2021). "Fourth, considering both COPD and smoking subjects, transcripts for IL-10 correlated inversely with radiographically-defined emphysema extent, but not with spirometry." (PMID 24805101, 2014). "The production of IL-10 and IL-13 in this large cohort further did not correlate with the severity of emphysema or airway obstruction (Figure A2 in Appendix)." (PMID 22969766, 2012).
emphysema (continued). "Although IL-17 response to EFs persisted in the emphysema group, there was no increase in response and as expected, there were no discernable changes in IL-10 or IL-13 responses in either group (data not shown)." (PMID 22969766, 2012). "However, among the Group A and Group B subjects for whom analyzable (non-contrast) CT scans were available (n = 17), IL-10 transcripts did show a significant inverse correlation with emphysema score, as determined by non-parametric Spearman correlation (rS = −0.54; p = 0.026)." (PMID 24805101, 2014). "We have previously reported a positive correlation between increase in IFN-γ and IL-10, but not IL-4 or IL-13, responses to EFs from CD4+ T cells isolated from former smokers with emphysema severity." (PMID 22969766, 2012).
falciparum malaria (20 papers, 2012 to 2025). "The IL-10 production during MiP-associated chronic inflammation is a hallmark of falciparum malaria during pregnancy that had been associated with poor pregnancy outcomes and considered as a possible MiP biomarker." (PMID 31805150, 2019). "We therefore, determined Cytokine profiles (IFN-γ, TNF-α, IL-6, TGF-β and IL-10) associated with Plasmodium falciparum malaria and soil borne helminth co-infections among patients attending Kampala International University Teaching Hospital in Uganda." (PMID 29560020, 2018). "We have previously shown that circulating levels of IL-10 were closely associated with the concentration of serum hepcidin in children with acute falciparum malaria." (PMID 24520384, 2014). "It was reported that non-Vγ9 γδT cells in the peripheral blood of patients with naturally acquired immunity against falciparum malaria had the potential to expand and produce IL-10 and IFN-γ." (PMID 35127555, 2021). "The balance between Th1 cytokines (TNF-α, IFN-γ) and Th2 cytokines (IL-10, IL-4) has been shown to be critical in the development of severe falciparum malaria with IL-10 shown to downregulate the functional activity and the production of TNF-α in Pf infection." (PMID 33604551, 2019). "Co-infected individuals expressed significantly higher levels of IL-10 (304 pg/ml) as compared to Plasmodium falciparum malaria infected individuals (11.57 pg/ml) and soil borne helminths infected individuals (77.01 pg/ml)." (PMID 29560020, 2018). "In conclusion, our study demonstrates an up-regulation of IFN-γ during Plasmodium falciparum malaria and an up-regulation of IL-10 and TGF-β during soil borne helminth infections." (PMID 29560020, 2018). "Soil borne helminths infected individuals expressed higher levels of IL-10 (73.86 pg/ml) as compared to Plasmodium falciparum malaria (33.64 pg/ml) and healthy individuals (26.09 pg/ml)." (PMID 29560020, 2018). "When IL-10 levels were similarly compared soil borne helminths infected individuals expressed higher levels of IL-10 (73.86 pg/ml) as compared to Plasmodium falciparum malaria (33.64 pg/ml) and healthy individuals (26.09 pg/ml)." (PMID 29560020, 2018). "Cytokine levels significantly differed across Plasmodium falciparum malaria, soil borne helminth infected patients and patients co-infected with Plasmodium falciparum malaria and soil borne helminth for IL-10 (P = 0.004), IL-6 (P = 0.011) and TGF-β (P = 0.003)." (PMID 29560020, 2018). "To determine whether non-Vγ9 γδ T cells produce IL-10 in patients with falciparum malaria, we used intracellular staining for IL-10 and confirmed that IL-10 was indeed produced in non-Vγ9 γδ T cells after whole PBMCs were cultured for 10 days." (PMID 28769886, 2017). "Contrary to the recent suggestion that P. vivax elicits more inflammation than P. falciparum, we found higher IL-10/TNF-α, IL-10/IFN-γ and IL-10/IL-6 ratios, but similar inflammatory cytokine responses per parasitized red blood cell, in vivax compared to falciparum malaria." (PMID 22973442, 2012). "Among the eight cytokines tested in this large cohort of adults with imported falciparum malaria, only MIF and IL-10 were higher in patients with greater disease severity." (PMID 37365194, 2023). "Additionally, the GOs up-regulated in the 3 forms of falciparum malaria were assessed and in MM analysis showed biological processes related to biogenesis, host metabolic processes, DNA damage repair activities and anti-inflammation with the up-regulation of IL-10." (PMID 34565410, 2021). "We note that Tanzanian children with falciparum malaria have markedly increased PBMC arginase 1 and IL-10, reduced PBMC NOS2 and plasma arginine, and monocytes expressing markers of alternative activation (M2-like monocytes)." (PMID 27385484, 2016).
falciparum malaria (continued). "However, a recent study on vivax malaria has revealed higher IL-10/TNF-α, IL-10/IFN- γ, and IL-10/IL-6 ratios, but similar inflammatory cytokine responses per parasitized erythrocyte, when compared to falciparum malaria." (PMID 34790829, 2021). "We show here that children with falciparum malaria have significantly increased levels of PBMC arginase 1 mRNA and protein, elevated plasma arginase activity, decreased PBMC NOS2 mRNA, and dramatically increased plasma levels of IL-10." (PMID 27385484, 2016). "Conversely, IL-10 (anti-inflammatory), primarily produced by IFN-γ+ Th1 cells and regulatory T cells in response to chronic antigenic stimulation, counteracts inflammation and limits immunopathology, a phenomenon frequently observed in asymptomatic falciparum malaria." (PMID 41279035, 2025). "Compared to control children (n = 106), children with moderately severe (n = 77) and severe falciparum malaria (n = 129) had significantly higher mononuclear cell arginase 1 mRNA, protein, and enzyme activity; lower NOS2 mRNA; lower plasma arginine; and higher plasma IL-10, IL-13, and IL-4." (PMID 27385484, 2016).
hematoma (20 papers, 2014 to 2025). A hematoma is a collection of blood from a vascular structure into an extravascular space. "Increased serum levels of IL-6 and IL-10 were detected in intraparenchymal hemorrhage, and higher admission IL-6 levels were associated with unfavorable 90-day functional outcomes and hematoma and perihematomal edema volumes." (PMID 36439158, 2022). "In the context of hemorrhagic stroke and hydrocephalus, plasma IL-10 levels are significantly associated with adverse outcomes like re-bleeding and hematoma expansion." (PMID 32106601, 2020). "In spontaneous ICH, higher plasma IL-10 levels on admission are associated with hematoma expansion and worse 30-day outcomes." (PMID 28659854, 2017). "Using our screening strategy for therapeutic efficacy in ICH, we show that our VCAM-LNPs, when loaded with IL-10 mRNA, lead to smaller hematoma sizes and improved behavioral outcomes in the mice." (PMID 40297702, 2025). "Syk potentially mediates Th2-polarized cytokine secretion (Il-6/Il-10), Cd36 enhances hematoma resolution via Il-10/Stat3 signalling and Cd74 synergizes with MIF to amplify inflammatory cascades." (PMID 40623122, 2025). "Treatment with VCAM-LNPs containing IL-10 mRNA led to ~69% reduction in hematoma size at 72 hours after ICH and ~65% improvement in motor behavior in our model, with no improvement in vascular leakage." (PMID 40297702, 2025). "The concentrations of cytokine IL6/IL8/IL10/VEGF in the hematoma fluid of the observation and control groups were significantly higher than those in venous blood (P < .001)." (PMID 38914867, 2024). "More importantly, higher levels of IL-10 in the hematoma and serum and lower amounts of M1 microglia were independently associated with a better recovery at 90 days after ICH." (PMID 35308167, 2022). "Higher plasma IL-10 levels were related to the hematoma expansion in spontaneous ICH and worse 30-day outcomes." (PMID 36439158, 2022). "Then, the levels of IL-6, IL-8 and IL-10 in the capsule of the hematoma were further measured to evaluate the inflammatory response." (PMID 34813498, 2021). "Previous studies have shown that IL-10 protects the nerve cells of peri-hematoma after ICH, and that the up regulation of IL-10 alleviates neurological deficits in patients with ICH." (PMID 34975411, 2021). "The level of anti-inflammatory cytokine IL-10 was also significantly enhanced in fracture hematoma compared to peripheral serum." (PMID 32325892, 2020). "Another study has found that patients with high concentrations of anti-inflammatory cytokine IL-10 also had high values for IL-6 and CXCL8, in addition to a tendency to be associated with a separated or layer type of hematoma." (PMID 29107999, 2017). "We found that rapamycin also decreased the level of IFN-γ and increased the level of IL-10 both in serum and around the hematoma in the autologous blood-injection model." (PMID 24602288, 2014). "We also used ELISAs to test the levels of IL-6, IL-8 and IL-10 in the capsule of the hematoma." (PMID 34813498, 2021). "In addition, there were higher concentrations of IL-6, IL-8, and IL-10 in the hematoma fluid than in the serum." (PMID 34813498, 2021). "In the earlier prospective cohort study of these two researchers on 57 patients, an association between increased hematoma fluid (but not serum) of a panel of biomarkers considered an anti-inflammatory index (IL-4, IL-5, IL-10, IL-13, IL-1 RA) and a reduced risk of recurrence was indicated." (PMID 37510193, 2023). "We leverage this targeting strategy to deliver IL-10 mRNA after ICH and show this has therapeutic effect in decreasing hematoma size and improving motor behavior." (PMID 40297702, 2025). "Anti-inflammatory, pro-survival regulators were highly expressed at delayed time points in ICH patients with a favorable outcome, and IL10 expression showed a negative correlation to high hematoma volume." (PMID 33564466, 2021).
hematoma (continued). "In both blood and hematoma fluid, inflammatory cytokines such as tumor necrosis factor (TNF)-α, interleukin (IL)-6 and IL-10 raise, and the anti-inflammatory activities in the hematoma may play a role in the risk of a recurrence of CSDH." (PMID 32328124, 2020). "Similar to our data, increased IL1-beta, IL6 and IL8 (protein levels) were detected early in hematoma while we did not see a clear increase in IL10, IL1R or VEGF early (although at mRNA levels rather than protein)." (PMID 32054088, 2020). "At 2 days post-bleed, IL-10 levels correlate with IL-6 levels, and IL-6 levels correlate with hematoma volume and mass effect, but IL-10 does not." (PMID 28659854, 2017). "IL10 expression showed a negative correlation in patients with high hematoma volume (>30 mL)." (PMID 33564466, 2021). "Compared with the sham group, TNF-α, IL-6, and IL-10 in hematoma increased significantly in the CSDH group (TNF-α: 26.51 ± 5.35 vs 250.31 ± 26.99 pg/ml, P < 0.01; IL-6: 25.76 ± 6.39 vs 112.77 ± 6.91 pg/ml, P < 0.01; IL-10 : 17.60 ± 1.53 vs 82.76 ± 8.12 pg/ml, P < 0.01." (PMID 32328124, 2020). "We observed a significant increase in IL-10, TGF-β, and Arg1 (M2 markers) on day 3, and the levels reduced from day 7 until day 28 on the hematoma side, and no significant changes were detected on the other side." (PMID 37190062, 2023).